MS4A15 (membrane spanning 4-domains A15)
Description:
May be involved in signal transduction as a component of a multimeric receptor complex.
Tractability: Antibody: UniProt predicts a signal peptide or a membrane-spanning region; its Gene Ontology location is reachable by antibodies, with medium confidence; the Human Protein Atlas places it where antibodies can reach.
Gene: Protein-coding gene on chromosome 11 (60,756,863 to 60,776,733, forward strand). Ensembl gene ENSG00000166961.
Subcellular location: Membrane
Subcellular location (Human Protein Atlas): Plasma membrane; Cytosol
Gene Ontology:
Biological process: cell surface receptor signaling pathway
Cellular component: plasma membrane; membrane
Genetic constraint (gnomAD): Loss-of-function variants: 22 observed, 20.69 expected, observed/expected ratio (o/e) 1.06, 90% interval 0.76 to 1.52. The upper end of that interval is the gene's LOEUF score, 1.52, which puts it in group 6 of 6, group 1 being the genes least tolerant of losing a copy. Missense variants: 301 observed, 308.49 expected, observed/expected ratio (o/e) 0.98, 90% interval 0.89 to 1.07. Synonymous variants: 124 observed, 121.21 expected, observed/expected ratio (o/e) 1.02, 90% interval 0.88 to 1.19.
Homologues: Orthologues: chimpanzee MS4A15 (97% identical), macaque MS4A15 (90% identical), pig MS4A15 (90% identical), rat Ms4a15 (86% identical), rabbit MS4A15 (82% identical), mouse Ms4a15 (80% identical), guinea pig MS4A15 (79% identical), zebrafish ms4a17a.11 (27% identical), zebrafish si:ch73-56d11.5 (27% identical), zebrafish ms4a17a.10 (27% identical), zebrafish ms4a17a.12 (27% identical), zebrafish ms4a17a.4 (26% identical), and 20 more. Paralogues in human: MS4A8 (35% identical), MS4A12 (32% identical), MS4A18 (29% identical), MS4A4A (26% identical), MS4A1 (23% identical), MS4A6A (23% identical), MS4A2 (22% identical), MS4A7 (22% identical), MS4A10 (22% identical), MS4A14 (20% identical), MS4A3 (20% identical), MS4A4E (19% identical), and 4 more.
Diseases named in the same sentence as MS4A15 in open-access papers:
MS4A15 is named in the same sentence as 8 diseases in open-access papers, as found by Europe PMC text mining. Sharing a sentence is not in itself a finding about the gene and the disease. The quoted sentences say what the papers report.
lung carcinoma (2 papers, 2022 to 2023). "A defective cell migration phenotype is thus consistent with decreased metastasis/increased survival of lung cancer patients with high MS4A15-expressing tumors." (PMID 34663908, 2022). "We further noted that despite high expression in primary adenocarcinomas, MS4A15 is lost in cultured lung cancer cell lines in a direct relationship to cell adhesion markers." (PMID 34663908, 2022). "Results indicated a significant downregulation of CX3CL1, MS4A15, and GSTA1 in lung cancer cells, while EPS8L3, G6PD, KRT6A, and S100P were notably upregulated, in line with the bioinformatics analysis findings." (PMID 37315289, 2023).
colon cancer (1 paper, 2020). "By studying colon cancer pathologic specimens, we confirmed that DYDC2, MS4A15, MAGEA1, WNT7A, APOD, and SERPINE1 were highly expressed in colon cancer tissues." (PMID 33680915, 2020).
lung adenocarcinoma (1 paper, 2023). A carcinoma that arises from the lung and is characterized by the presence of malignant glandular epithelial cells. "According to the Kaplan-Meier curve, patients with lung adenocarcinoma having poor expression of MS4A2, MS4A7, MS4A14, and MS4A15 had a low overall survival rate." (PMID 37533433, 2023).
ovarian carcinoma (1 paper, 2024). A malignant neoplasm originating from the surface ovarian epithelium. "Additionally, our literature review revealed the upregulation of the MS4A15 gene has been observed in both STAD and ovarian cancer." (PMID 38840833, 2024).
renal carcinoma (1 paper, 2023). A carcinoma arising from the epithelium of the renal parenchyma or the renal pelvis. "For examples, in renal cancer, MS4A15 regulates anti-ferroptotic lipid reservoirs to provide a key resistance mechanism that is distinct from antioxidant and lipid detoxification pathways." (PMID 37576602, 2023).
cancer (1 paper, 2025). A tumor composed of atypical neoplastic, often pleomorphic cells that invade other tissues. "One Hako relic contains the transcription start site of MS4A15 (membrane spanning 4-domains A15), a gene that increases proliferation and ferroptosis resistance of cancer cells." (PMID 40083010, 2025).
MS4A15 also shares sentences with these, for which no sentence is quoted: adenocarcinoma (1 paper); glioma (1).